AFG3L1P (AFG3 like matrix AAA peptidase subunit 1, pseudogene )
Synonyms: AFG3; AFG3L1
Gene: Long non-coding RNA gene on chromosome 16 (89,972,581 to 90,002,161, forward strand). Ensembl gene ENSG00000293510.
Diseases named in the same sentence as AFG3L1P in open-access papers:
AFG3L1P is named in the same sentence as 3 diseases in open-access papers, as found by Europe PMC text mining. Sharing a sentence is not in itself a finding about the gene and the disease. The quoted sentences say what the papers report.
lung carcinoma (1 paper, 2017). "In network, 4 pseudogenes (RRP7B, RPLP0P2, MSTO2P and AFG3L1P) co-methylated with EZH2, suggesting an involvement in the progression of lung cancer." (PMID 28938616, 2017).
AFG3L1P also shares sentences with these, for which no sentence is quoted: bone marrow failure (1 paper); Fanconi anaemia (1).